HLA-DRA (major histocompatibility complex, class II, DR alpha)
Diseases named in the same sentence as HLA-DRA in open-access papers (continued):
Sharing a sentence is not in itself a finding about the gene and the disease.
glioma (10 papers, 2015 to 2025). A benign or malignant brain and spinal cord tumor that arises from glial cells (astrocytes, oligodendrocytes, ependymal cells). "In contrast, in low-grade gliomas, HLA-DRA expression level was linked to immune infiltration; a high expression of HLA-DRA was associated with a poor prognosis." (PMID 40565031, 2025). "For the tissue brain cortex, one of the most similar nodes was the gene major histocompatibility complex, class II, DR alpha (HLA-DRA) which is shown to be elevated in expression in gliomas." (PMID 35903362, 2022). "Then, we used the HPA to verify the HLA-DRA gene expression in glioma cells and glial brain cells." (PMID 35585639, 2022). "Additionally, our results identified specific immune-related molecules—TNFSF4, HLA-DRA, and ENTPD1—that were significantly correlated with the crotonylation-associated risk score, further linking crotonylation pathways to the regulation of the immune microenvironment in gliomas." (PMID 40636690, 2025). "The results of the DEG co-expression network showed that the HLA family (HLA-A, HLA-B, HLA-C, HLA-E, HLA-DRA, HLA-DRB1, and CD74 [HLADG]) plays a vital role in the network, suggesting that tumor immunity is involved in glioma formation." (PMID 34660294, 2021). "The mechanism of HLA-DRA in gliomas is not currently known, but our study validates the relevance of HLA-DRA to the tumor immune microenvironment." (PMID 35585639, 2022). "We found that the HLA-DRA gene was not expressed in normal glial cells (patient ID: 1371; 3731; 3739) but was highly expressed in glioma cells (patient ID: 3137; 3120; 3174)." (PMID 35585639, 2022). "The results showed that HLA-DRA was not expressed in glioma cells but significantly expressed in glioma cells." (PMID 35585639, 2022). "Clinical correlation analysis of HLA-DRA showed that there was higher expression of HLA-DRA in grade III, which indicated that HLA-DRA could promote tumor development and serve as a reference for the utility of gene therapy in glioma." (PMID 35585639, 2022).
systemic lupus erythematosus (10 papers, 2013 to 2025). An autoimmune multi-organ disease typically associated with vasculopathy and autoantibody production. "Five loci in HLA-DRA are associated with different autoimmune diseases like systemic lupus erythematosus or multiple sclerosis." (PMID 34635054, 2021). "Genes that were significant with at least two variables include: BTNL2 for alopecia areata, NOD2 for Crohn’s disease, PLA2R1 for membranous neuropathy, LMO1 for neuroblastoma, and TNPO3, UBE2L3, HLA-DRA, and HIC2 for systemic lupus erythematosus." (PMID 26170196, 2015). "By KEGG pathway analysis, six genes, i.e., C4A, C4B, FCGR2A, HLA-DMA, HLA-DRA, and HLA-DRB1, were enriched as the top 2 significant results in the pathways of Staphylococcus aureus infection (KEGG term hsa05322, FDR = 1.42E−05) and systemic lupus erythematosus (KEGG term hsa05150, FDR = 2.00E−04)." (PMID 34804021, 2021).
multiple sclerosis (9 papers, 2012 to 2024). A progressive autoimmune disorder affecting the central nervous system resulting in demyelination. "Polymorphisms of rs4935356, rs3177928, and rs7197 of the HLA-DRA gene have been associated with multiple sclerosis in the Iranian population." (PMID 36132072, 2022). "SAIF’s high genetic risk on multiple sclerosis is based on a rare heterozygous AG variant at rs3135388 in HLA-DRA, which appears in 4% GIH individuals." (PMID 22938532, 2012). "HLA-DRA is shown to be a susceptibility gene for multiple sclerosis in the Australian population." (PMID 36132072, 2022). "Variants in HLA-DRA have been associated with Parkinson disease and multiple sclerosis, but not with AD." (PMID 23227193, 2012).
asthma (8 papers, 2017 to 2025). "HLA-DQB1 and HLA-DRA have both been previously been associated with asthma, but each has also been associated to another phenotype; HLA-DQB1 to hypothyroidism and HLA-DQB1 to RA." (PMID 32245788, 2020). "HLA-DRA is associated to asthma but also associated to the presence of nasal polyps in a cohort of asthmatic patients." (PMID 29253858, 2017). "Finally, HLA-DRA contains a nonsynonymous SNP in a coding region previously associated with asthma development in an independent dataset." (PMID 32245788, 2020). "Recent research utilizing an animal model has shown that ACO mice exhibit significantly more extensive inflammation compared to those with COPD or asthma, with antigen presentation pathways, such as HLA-DRA, playing a key role." (PMID 41462706, 2025). "A recent single-cell RNA sequencing analysis found that pediatric patients with HDM-sensitized asthma displayed increased expression of the HLA-DRA and HLA-DRB1 genes in their PBMCs." (PMID 41462706, 2025). "A recent study reported colocalizations between eQTLs for HLA-B, HLA-DQB1, HLA-DQA1, HLA-DRA, TAP1, and RNF5 in induced pluripotent stem cells with asthma GWAS SNPs." (PMID 35606880, 2022). "For example, HLA-DRA, HLA-DOA, and HLA-DQA1 are all components of pathways that play a role in hypothyroidism, RA, asthma, and antigen processing and presentation." (PMID 32245788, 2020). "Gene expression levels of the HLA-DRA (1.01 ± 0.43 versus 0.67 ± 0.23-fold change, adjusted p = 0.019) and HLA-DRB1 (1.42 ± 0.74 versus 0.81 ± 0.36-fold change, adjusted p = 0.011) genes were both elevated in the COPD-only group compared to the asthma-only group." (PMID 41462706, 2025). "Enriched KEGG pathways could be strongly related to inflammatory processes and regulation in the mixed-cell analysis (with TNF and the HLA, human leukocyte antigen, loci HLA-DRA and HLA-DOB largely contributing to this finding), including the KEGG pathway “Asthma”." (PMID 33076907, 2020).
cervical cancer (7 papers, 2017 to 2025). A primary or metastatic malignant neoplasm involving the cervix. "Background and Objectives: Abnormal expressions of CD74 and human leukocyte antigen-DR alpha (HLA-DRA) have been reported in various cancers, though their roles in cervical cancer remain unclear." (PMID 35208514, 2022). "HLA-DRA expression was associated with increased disease-free and disease-specific survival, suggesting that HLA-DRA could be a promising biomarker for developing immunotherapies for cervical cancer." (PMID 40565031, 2025). "The roles of CD74 and HLA-DRA in cervical cancer development are relatively unknown." (PMID 35208514, 2022).
ovarian carcinoma (7 papers, 2017 to 2025). A malignant neoplasm originating from the surface ovarian epithelium. "Based on expression of 21 CAF‐associated markers, we defined four subtypes of CAFs in ovarian cancer as follows: myofibroblast CAFs (myCAFs, 0: SMA+, 1: FAP+, 2: COL1A1+) and antigen‐presenting CAFs (apCAFs, 3: CD74+/HLA‐DRA+)." (PMID 40126173, 2025). "This protein is generally invariable, yet research showed HLA-DRA was highly overexpressed in ovarian cancer, perhaps as a result of inflammatory events in the tumor microenvironment." (PMID 28245581, 2017). "MSLN was positively correlated with immunosuppressive genes in ovarian cancer, such as LGALS9, CD276, TMIGD2, CD200, TNFRSF14, and human leukocyte antigen (HLA)-related families including HLA-DRA, HLA-DRB1, HLA-DPA1, HLA-DMA, HLA-E, etc.." (PMID 35692779, 2022).
rheumatoid arthritis (7 papers, 2013 to 2024). A chronic, systemic autoimmune disorder characterized by inflammation in the synovial membranes and articular surfaces. "KEGG pathway analysis of the upregulated proteins in ENTPD1+CD55+ cells indicated enrichment for proteins involved in rheumatoid arthritis (e.g., HLA-DRA, ICAM1) and ECM–receptor interaction (e.g., type I collagen, Laminin subunit alpha-5, integrin-subunit alpha-6)." (PMID 38612896, 2024). "As with the original DMG-alone analysis, the MEGs were also significantly 3.75-fold enriched in the KEGG ‘Rheumatoid arthritis‘ pathway (q = 1.70E-02, where q is a multiple-test corrected P-value) with 7 out of 89 genes: ANGPT1, CSF2, CTLA4, HLA-DQA1, HLA-DQA2, HLA-DRA and HLA-DRB1." (PMID 25901943, 2015).
type 1 diabetes (7 papers, 2011 to 2026). "Additionally, the type I diabetes mellitus pathway (ssc04940) showed associations with genes such as HLA-DRA, SLA-DQA, SLA-DQB1, and MHC class II, DM beta (SLA-DMB), along with other pathways." (PMID 39021677, 2024). "Whereas in our pathway analysis, more genes are identified as part of Type I diabetes mellitus and Allograft rejection pathways (i.e. CD28, HLA-B, HLA-C, HLA-DMB, HLA-DPA1, HLA-DQA2, HLA-DRA, IL12A)." (PMID 22046267, 2011).
autoimmune disease (6 papers, 2020 to 2024). A disorder resulting from loss of function or tissue destruction of an organ or multiple organs, arising from humoral or cellular immune responses of the individual to their own tissue constituents. "The relationship between HLA-DRA gene polymorphisms and autoimmune diseases has been studied." (PMID 36132072, 2022). "Both ICOSLG and HLA-DRA are known to be involved in immunity, and considering that MS is a type of autoimmune disease, perhaps this relationship explains the mechanism of rs4819388 and rs3177928 in MS and indicates that ICOSLG, HLA-DRA may be associated with MS." (PMID 32117605, 2020).
gastric cancer (6 papers, 2020 to 2025). A primary or metastatic malignant neoplasm involving the stomach. "Our study provided strong evidence for the underlying mechanisms by which genetic variation, methylation, and gene expression of HLA-DRA were associated with the trait of gastric cancer." (PMID 38877387, 2024). "Three-step SMR analysis showed that a putative mechanism, cg17294865 CpG site regulating HLA-DRA expression was negatively associated with gastric cancer risk." (PMID 38877387, 2024). "This study provides evidence that upregulating the expression level of HLA-DRA can reduce the risk of gastric cancer." (PMID 38877387, 2024). "Our study showed that HLA-DRA was specifically highly expressed in monocytes/macrophages and myeloid cells and reduced the risk of gastric cancer." (PMID 38877387, 2024). "Previous studies have shown that HLA-DRA was associated with the risk of gastric cancer development." (PMID 38877387, 2024). "Our study suggested that elevated levels of HLA-DRA expression and higher methylation levels may reduce the risk of gastric cancer." (PMID 38877387, 2024). "Through Mendelian randomization analysis and single-cell analysis, our results suggest a potential pathogenic mechanism that the expression level of HLA-DRA, which is mainly expressed in monocytes/macrophages and myeloid cells, is inversely correlated with the risk of gastric cancer." (PMID 38877387, 2024). "Finally, single cell type expression analysis provides updated insights into the underlying pathogenesis of HLA-DRA in gastric cancer." (PMID 38877387, 2024). "Higher methylation levels (Betasmr = -0.09) and elevated levels of HLA-DRA expression (Betasmr = -0.33) may reduce the risk of gastric cancer." (PMID 38877387, 2024). "Therefore, it was speculated that a putative mechanism may be that genetic variation up-regulates HLA-DRA expression levels by affecting CpG island shore status, which in turn reduces the risk of gastric cancer." (PMID 38877387, 2024). "HLA-DRA was significantly differentially expressed in monocyte/macrophage and myeloid cells in gastric cancer." (PMID 38877387, 2024). "Subsequently, by integrating GWAS data for GI cancer with e/mQTL from peripheral blood, we identified several possibilities but prioritized an adaptive immune-related gene (HLA-DRA) and a methylation site (cg17294865) in gastric cancer." (PMID 38877387, 2024). "Our results show that methylation locus cg17294865 (PPH4 = 0.82) and gene HLA-DRA (PPH4 = 0.77) share a genetic figure with gastric cancer." (PMID 38877387, 2024). "We found that 2 genes, HLA-DRA (Betasmr = -0.33) and HLA-DPB1 (Betasmr = -0.18), were negatively associated with gastric cancer." (PMID 38877387, 2024). "Second, the posterior probability PPH4 of co-localization of the HLA-DRA gene with gastric cancer GWAS in our study was 0.77, but PPH4 ≥ 0.80 was considered strong evidence of Bayesian co-localization." (PMID 38877387, 2024). "To investigate whether there was a cell type-specific enrichment of HLA-DRA, an adaptive immune-related coding gene, we performed cellular expression analysis by analyzing single-cell RNA-seq data of gastric cancer from the GEO database." (PMID 38877387, 2024). "Furthermore, we further clarified the differential expression of HLA-DRA in monocytes/macrophages and myeloid cells in gastric cancer through single-cell omics studies." (PMID 38877387, 2024). "However, the potential mechanism of HLA-DRA in gastric cancer had not been characterized." (PMID 38877387, 2024).
lung adenocarcinoma (6 papers, 2019 to 2025). A carcinoma that arises from the lung and is characterized by the presence of malignant glandular epithelial cells. "As to their prognostic values, seven genes could not predict the clinical outcome in NSCLC and lung squamous cell carcinoma (LUSC), while CD2 and HLA-DRA were associated with the improved prognosis in lung adenocarcinoma (LUAD)." (PMID 35794593, 2022). "The top genes of activated neutrophils, namely HLA‐DPA1, HLA‐DRA, and HLA‐DRB1, were found to be associated with a good prognosis in lung adenocarcinoma (LUAD)." (PMID 38483933, 2024). "For both HLA-DPA1 and HLA-DRA, the rank of correlations is highest in cutaneous melanoma, followed by lung adenocarcinoma, sarcoma and breast invasive carcinoma." (PMID 31212865, 2019). "In lung adenocarcinoma, high expression of CCL20, IL23A, MMP1 and MMP3 was significantly associated with poor patient prognosis, whereas high expression of FOS, HLA-DPA1, HLA-DPB1, HLA-DQA1, HLA-DQB1 and HLA-DRA was significantly associated with improved patient prognosis." (PMID 40016789, 2025).
sarcoidosis (6 papers, 2012 to 2025). Sarcoidosis is a multisystemic disorder of unknown cause characterized by the formation of immune granulomas in involved organs. "We replicated associations for several previously reported sarcoidosis susceptibility risk loci in our AA collection including MHC Class II region genes (HLA-DRA, HLA-DRB5, HLA-DRB1, and HLA-DQA1), BTNL2, RAB23, and ANXA11." (PMID 22952805, 2012). "In conclusion, we found novel SNPs in BTNL2 and HLA-DRA regions associating with sarcoidosis." (PMID 28469621, 2017). "Our finding further establishes that polymorphisms in the HLA-DRA and BTNL2 have a role in sarcoidosis susceptibility." (PMID 28469621, 2017). "Five SNPs were associated with the disease course of sarcoidosis (BTNL2 exonic SNP rs28362677, BTNL2 promoter SNP rs5007259, SNPs rs3135351 and rs3129843 between genes BTNL2 and HLA-DRA, and HLA-DRA downstream SNP rs3129877)." (PMID 28469621, 2017). "Six SNPs [rs9268528 (BTNL2 promoter), rs3135351, and rs3129843 (between genes HLA-DRA and BTNL2), rs9268644 and rs3129877 (HLA-DRA intronic), rs6937545 (downstream of HLA-DRA)] were associated with the disease course of sarcoidosis." (PMID 28469621, 2017). "To detect variants predisposing to sarcoidosis and to identify genetic differences between patient subgroups, we studied four genes in the MHC Class III region (LTA, TNF, AGER, BTNL2) and HLA-DRA with tag-SNPs and their relation to HLA-DRB1 alleles." (PMID 28469621, 2017). "Interestingly, HLA-DRA has shown to have SNP–SNP interaction with ANXA11, another sarcoidosis associated gene." (PMID 28469621, 2017). "Both rs3177928 and rs6937545 are also cis-acting eQTL affecting the expression of HLA-DRB1 and are not in LD with other HLA-DRA gene variants previously associated with sarcoidosis." (PMID 28469621, 2017). "Reanalysis of a sarcoidosis scRNA-seq dataset revealed that, similar to NL and NXG, sarcoidosis lesional fibroblasts expressed high levels of MHC (e.g., HLA-B and HLA-DRA), CD74, PLOD2, STAT1, TNC, PRSS23, PSMB9, and CXCL9." (PMID 39989459, 2025).
bladder cancer (5 papers, 2021 to 2024). "Previous studies have confirmed that HLA-DRA is associated with the prognosis of ccRCC and bladder cancer." (PMID 37260987, 2023). "HLA-DRA is highly expressed in bladder cancer tissues than corresponding adjacent tissues and indicates poor progression-free survival." (PMID 34136377, 2021).
cutaneous melanoma (5 papers, 2017 to 2024). A primary melanoma arising from atypical melanocytes in the skin. "HLA-DRA, a key biomarker linked to the development and progression of skin cutaneous melanoma, ranks as the 46th most strongly associated gene with this disease." (PMID 39763976, 2024). "Nevertheless, the frequency of the somatic mutations that we detected both in IDO1 and HLA-DRA, suggests that these are common events taking place in skin melanoma and could be involved in hindering patient response to ICI therapies." (PMID 36389735, 2022). "Our data reveal that IDO1 and HLA-DRA are frequently mutated in skin melanoma, but these mutations do not seem to associate with their gene expression." (PMID 36389735, 2022). "HLA-DRA is the 46th most closely correlated gene in cutaneous melanoma." (PMID 31212865, 2019).
colon cancer (4 papers, 2019 to 2025). "Notably, relationships between VSIG4, HLA-DRA, and HLA-DRB6 were observed in this study, indicating that VSIG4 may mediate the expression of HLA-DR family genes through antigen presentation and be involved in the immune activation mechanism of MSI colon cancer." (PMID 39726813, 2024).
colorectal cancer (4 papers, 2020 to 2024). A primary or metastatic malignant neoplasm that affects the colon or rectum. "The expression of class II MHC antigens, including HLA-DRA and HLA-DRB, has been chronically considered a crucial step in immune response toward colorectal carcinomas." (PMID 33392203, 2020).
Crohn disease (4 papers, 2015 to 2025). A gastrointestinal disorder characterized by chronic inflammation involving all layers of the intestinal wall, noncaseating granulomas affecting the intestinal wall and regional lymph nodes, and transmural fibrosis. "Amongst genes in SNP-associated bins, we found Crohn’s disease-associated genes STAT3, ATG16L1 and MHC genes HLA-DWB, HLA-DRA and HLA-DQA252." (PMID 29402885, 2018).
dementia (4 papers, 2019 to 2024). Loss of intellectual abilities interfering with an individual's social and occupational functions. "The phenotypic transformation from homeostatic microglia towards reactive microglia in dementia pathologies is associated with TREM2, HLA-DRA, ENTPD1 (CD39), CD80 (B7-1), CD86 (B7-2), CCR5, CD274, ITGAX (CD11c), TIMD4 and MRC1." (PMID 33113879, 2020). "Wild-type TREM2 carriers D11 (female, 48 years old was carrying ApoEɛ2/ɛ3, Tau H2/H2, TREM2C/C, and HLA-DR G/G) and D12 (male, 46 years old was carrying ApoEɛ3/ɛ3 Tau H2/H2, TREM2C/C, and HLA-DRA/G) had not developed dementia, indicating that H2 homozygosity could be protective in DS subjects." (PMID 30909239, 2019).
non-small cell lung carcinoma (4 papers, 2021 to 2025). A group of at least three distinct histological types of lung cancer, including non-small cell squamous cell carcinoma, adenocarcinoma, and large cell carcinoma. "Research showed that HLA-DRA can guide ICB in non-small cell lung cancer and ER-negative breast cancer." (PMID 38877387, 2024). "As for the distinctive potential of the gene in non-small cell lung cancer, researchers from MD Anderson Cancer reported in 2018 that HLA-DRA has different expression levels in the normal and tumor tissue sections in clinical FFPE samples." (PMID 34575089, 2021). "HLA-DRA has also been identified as a marker for cancer hotspots and may help predict therapeutic responses to anti-PD-1 immunotherapy in non-small-cell lung cancer." (PMID 40678806, 2025). "Therefore, our predicted gene HLA-DRA can also be an effective biomarker distinguishing different cell subtypes from different tissues in non-small cell lung cancers." (PMID 34575089, 2021).